REN (renin)
Diseases named in the same sentence as REN in open-access papers (continued):
Sharing a sentence is not in itself a finding about the gene and the disease.
Glucose intolerance (10 papers, 2012 to 2024). Glucose intolerance (GI) can be defined as dysglycemia that comprises both prediabetes and diabetes. "The activation of the renin–angiotensin–aldosterone system reduces potassium concentrations in the body, thereby inhibiting insulin release and increasing glucose intolerance." (PMID 37107973, 2023). "A high-fructose diet (60% fructose) in rodents has also been reported to cause metabolic disturbances, including elevated blood pressure, glucose intolerance, and hyperlipidemia, as well as a dysregulation of the renin–angiotensin system (RAS)." (PMID 28700686, 2017). "Consistent with previous studies of Ang II infusion and transgenic renin expression, male RenTgMK transgenic mice exhibited glucose intolerance, even on a low-fat diet." (PMID 23308073, 2012). "In summary, our data demonstrate that transgenic hepatic overexpression of renin leads to glucose intolerance, decreased fat mass, hypoinsulinemia, and hypotriglyceridemia, with normal systemic insulin sensitivity." (PMID 23308073, 2012). "We report here that elevated circulating Ang II due to renin overexpression leads to glucose intolerance, which is further exacerbated by high-fat feeding." (PMID 23308073, 2012). "Our results demonstrate that elevated circulating Ang II due to renin overexpression leads to glucose intolerance, but with consistently lower levels of plasma insulin." (PMID 23308073, 2012). "The paradoxical glucose intolerance despite low adiposity and low insulinemia in the renin transgenic male mice vs. control littermates led us to further investigate whether these differences were due to altered insulin sensitivity and/or glucose production or utilization in this model." (PMID 23308073, 2012).
Hypernatremia (10 papers, 2013 to 2025). An abnormally increased sodium concentration in the blood. "Given the significant hypernatremia and hyperchloremia in both mutant animals, we wondered whether the renin-angiotensin-aldosterone system (RAAS) or dehydration was activated in the mutant mice." (PMID 40289527, 2025).
kidney tumors (10 papers, 2014 to 2026). "However, there have been no reported cases of full-term delivery, particularly when it is caused by renin-secreting renal tumors." (PMID 39650950, 2024). "Juxtaglomerular cell tumor (JGCT), also known as reninoma, is a rare renin-secreting neoplasm of the kidney first described in 1967." (PMID 41357681, 2026). "Juxtaglomerular cell tumors (JCT) are uncommon renin‐secreting tumors of the kidney with cytologic findings of JCT rarely reported." (PMID 39568313, 2025). "Juxtaglomerular cell tumors (JCT), also known as reninomas, are a type of benign mesenchymal renin‐secreting tumor of the kidney, whereas metastasis is extremely rare." (PMID 39568313, 2025). "These factors make managing renin-producing renal tumors during pregnancy exceptionally challenging." (PMID 39650950, 2024). "As a result of this systematic search process, we identified eight case reports of renin-secreting renal tumors during pregnancy." (PMID 39650950, 2024). "The renin level of the patient was abnormally high, and a renal tumor was detected in the right kidney." (PMID 39650950, 2024). "We present the case of a 28-year-old pregnant patient who delivered with a renin-secreting renal tumor and provide a literature search of similar cases." (PMID 39650950, 2024). "Reninomas are exceedingly rare renin-secreting kidney tumours that derive from juxtaglomerular cells, specialised smooth muscle cells that reside at the vascular inlet of glomeruli." (PMID 37749094, 2023). "Histological examination of the excised tumor is essential for confirming the diagnosis of reninoma because other renal tumors can also secrete renin." (PMID 25177679, 2014). "The search keywords used were (pregnan* OR gestation*) AND (renin-producing OR renin-secreting OR reninoma OR juxtaglomerular) AND (tumor* OR neoplasm* OR cancer*) to identify relevant case reports of renin-secreting renal tumors during pregnancy." (PMID 39650950, 2024). "Further investigation revealed elevated blood renin levels and renal tumors." (PMID 39650950, 2024). "The concurrent presence of a renal neoplasm suggests the possibility of a renin-secreting tumor." (PMID 34859924, 2021).
malnutrition (10 papers, 2016 to 2025). Inadequate nutrition resulting from poor diet, malabsorption, or abnormal nutrient distribution. "First, animal experiments have revealed that prenatal and postnatal malnutrition can elevate blood pressure by altering the renin-angiotensin system, and increase blood glucose by destroying pancreatic β-cell function, which can then increase cardiovascular risk." (PMID 36148331, 2022).
migraine (10 papers, 2019 to 2025). "MR analysis revealed that the diuretics and agents that act on the renin‐angiotensin system were discovered to be associated with an increased risk of migraine and migraine with aura." (PMID 41261954, 2025). "Secondly, the mechanisms by which diuretics and agents acting on the renin‐angiotensin system affect the risk of migraines require validation through additional clinical studies and experimental evidence." (PMID 41261954, 2025). "The target NCF2, associated with Agents acting on the renin‐angiotensin system, is linked to a reduced risk of migraine with aura (OR (95% CI) = 0.674 (0.538−0.843), PSMR = 5.60×10−4)." (PMID 41261954, 2025). "Similarly, the shared target SLC12A1 of both Diuretics and Agents acting on the renin‐angiotensin system is also connected to a decreased risk of migraine with aura (OR (95% CI) = 0.954 (0.927−0.981) and PSMR = 1.08×10−3)." (PMID 41261954, 2025). "To achieve the objective, we initially conducted MR analyses using GWAS summary statistics for 14 medication categories and migraine and its subtypes, revealing that both diuretics and agents that act on the renin‐angiotensin system are positively associated with migraine and migraine with aura." (PMID 41261954, 2025). "The common targets C12orf76 (OR (95% CI) = 1.241 (1.034−1.488), PSMR = 2.01×10−2) and GPATCH4 (OR (95% CI) = 1.54 (1.205−1.969), and PSMR = 5.70×10−4) of both Diuretics and Agents acting on the renin‐angiotensin system are associated with a reduced risk of migraine." (PMID 41261954, 2025). "Similarly, while alpha-adrenoceptor blockers are linked to a higher risk of migraine, they, along with renin inhibitors, offer a protective effect against dorsalgianas." (PMID 39268473, 2024). "The effect of candesartan as a preventive treatment of migraine could be related to how the renin–angiotensin–aldosterone system affects the brain." (PMID 33589682, 2021). "Moreover, beneficial effects have been reported in cases of migraine and neuropathic and nociceptive pain for drugs that block RAAS activation versus renin inhibitors." (PMID 33855212, 2021).
primary immunodeficiency (10 papers, 2016 to 2024). "Type I exhibited six unique pathways, including amphetamine addiction, hematopoietic cell lineage, primary immunodeficiency, renin-angiotensin system, salivary secretion, starch, and sucrose metabolism." (PMID 34068143, 2021). "The GSEA results showed that the calcium signaling pathway, and the renin-angiotensin system were negatively related to WAC-AS1, and the cytosolic DNA sensing pathway, glycosylphosphatidylinositol GPI anchor biosynthesis, and primary immunodeficiency were positively linked to WAC-AS1 in SARC." (PMID 37248547, 2023). "The high BCL7A subgroup was enriched in pathways related to DNA replication, mismatch repair, primary immunodeficiency, and the low BCL7A subgroup was enriched in pathways such as Rig-I-like receptor signaling and the renin-angiotensin system." (PMID 39867577, 2024). "In particular, we detected that ZAP70 was enriched in primary immunodeficiency, TNFRSF4, and CXCL5 were enriched in cytokine-cytokine receptor interaction, CTSG was enriched in the renin-angiotensin system, and the CHRM2 and CTSG were enriched in neuroactive ligand-receptor interaction." (PMID 34133324, 2021).
secondary hyperparathyroidism (10 papers, 2009 to 2024). Overproduction of parathyroid hormone in response to influence external to the parathyroid glands. "Proposed mechanisms are effects on myocardial gene expression, the renin-angiotensin axis or through secondary hyperparathyroidism." (PMID 21241491, 2011). "Previous studies have also shown that treatment with renin-angiotensin-aldosterone system blockers, inflammation, and secondary hyperparathyroidism could be considered predictors of ESA hyporesponsiveness." (PMID 39518373, 2024). "Park and colleagues reported that calcitriol, administered intravenously twice weekly over 15 weeks, reduced left ventricular mass and suppressed circulating levels of renin, angiotensin II and ANP in patients on chronic hemodialysis with secondary hyperparathyroidism." (PMID 19178708, 2009). "Secondary hyperparathyroidism in vitamin D receptor-null mice may also contribute to renin upregulation, considering that intravenous infusion of PTH increases plasma renin activity and renin release." (PMID 26000280, 2015). "Potential mechanisms that may explain this link include involvement of vitamin D in the regulation of the renin-angiotensin system, and the negative vascular effects of secondary hyperparathyroidism." (PMID 19178708, 2009).
Ureteral obstruction (10 papers, 2015 to 2024). Obstruction of the flow of urine through the ureter. "Experiments on fetal sheep demonstrated that fetal partial ureteral obstruction can cause upregulation of the levels of renin, angiotensinogen and angiotensin receptors, which result in water and salt retention." (PMID 32787795, 2020). "We previously demonstrated that ureteral obstruction is associated with a urinary concentrating defect and reduced expression of renal aquaporins (AQPs), in which the renin–angiotensin system (RAS) may play an important role." (PMID 31572210, 2019). "For example, medications that block the renin–angiotensin system have been shown to affect the alterations induced by ureteric obstruction." (PMID 38338817, 2024). "In the UUO model, increased hydrostatic pressure due to ureteral obstruction activates renin‐angiotensin system (RAS), which leads to the production of Ang II." (PMID 37463875, 2023). "In mice with lithium induced nephrogenic diabetes or unilateral ureteral obstruction, models that are associated with reduced AQP2 kidney expression, renin inhibition for 7 days has been demonstrated to increase AQP2 expression." (PMID 37565514, 2023). "Exogenous Klotho expression suppressed the upregulation of AGT, renin, ACE, and AT1R protein expression and normalized blood pressure in 5/6 nephrectomised rats and unilateral ureteral obstruction (UUO) mice." (PMID 36059935, 2022). "Recently, it has been reported that in rat models with unilateral ureteral obstruction, MZR combined with a direct renin inhibitor inhibits tubulointestinal fibrous change and inflammation." (PMID 26433884, 2015). "The aims of the present study were to examine whether the renin inhibitor aliskiren could prevent the reduction in AQP expression and improve the urinary concentrating capacity in mice with bilateral ureteral obstruction (BUO) and BUO release." (PMID 31572210, 2019).
African trypanosomiasis (9 papers, 2018 to 2025). "The top 5 overrepresented KEGG pathways included renin-angiotensin system, graft-versus-host disease, African trypanosomiasis, fat digestion and absorption, and inflammatory bowel disease (IBD)." (PMID 35860693, 2022). "As shown, these DEGs were mainly enriched in Hematopoietic cell lineage, African trypanosomiasis, Rap1 signaling pathway, Renin secretion, and Chemokine signaling pathway." (PMID 34233597, 2021).
aneurysm (9 papers, 2012 to 2025). Bulging or ballooning in an area of an artery secondary to arterial wall weakening. "Besides playing a critical role in maintaining cardiovascular homeostasis, the renin–angiotensin–aldosterone system (RAS) has been strongly implicated in (aortic) aneurysm pathogenesis." (PMID 40003968, 2025). "Third, combination therapies concurrently targeting NETs and complementary pathways (e.g., MMPs, renin-angiotensin system) should be explored to achieve synergistic effects in established aneurysms." (PMID 41574096, 2025). "Despite the importance of the renin-angiotensin (Ang) system in abdominal aortic aneurysm (AAA) pathogenesis, strategies targeting this system to prevent clinical aneurysm progression remain controversial and unproven." (PMID 23226500, 2012). "Since AT1R signaling is involved in aneurysm growth in MFS mice, but we do not observe reduced aneurysm growth with C1-INH Cetor®, it may be concluded that the observed AT1R signaling in MFS mice is not dependent on renin but rather mediated by a local cue such as stretch-induced activation of AT1R." (PMID 36279189, 2022).
coagulopathy (9 papers, 2012 to 2025). "AAA is defined as a permanently weakened and dilated abdominal aorta, which develops due to inflammation of the tunica media, activation of the renin–angiotensin–aldosterone system, immune system activation, and coagulation disorders." (PMID 40244390, 2025). "Although the exact cause of AAA remains unknown, factors that trigger an inflammatory state at the level of the tunica media, along with the renin–angiotensin–aldosterone system (RAAS), immune system activation, and coagulation disorders, are all believed to play a causal role." (PMID 40244390, 2025). "Some other lesser known risk factors that could predispose to SPS mediated intestinal injury are previous abdominal surgery, elevated renin, immunosuppression, antibiotic therapy, preceding irradiation, diverticular disease, coagulation disorder, opportunistic infections, and uremia." (PMID 23476770, 2012). "This article primarily reviews the relevant foundational research, focusing on disruptions in the renin-angiotensin-aldosterone system (RAAS), immune system activation, and coagulation disorders." (PMID 39742024, 2024).
Gitelman syndrome (9 papers, 2019 to 2025). Gitelman syndrome (GS), also referred to as familial hypokalemia-hypomagnesemia, is characterized by hypokalemic metabolic alkalosis in combination with significant hypomagnesemia and low urinary calcium excretion. "Vascular volume depletion is also associated with Gitelman’s syndrome, which results in elevated plasma renin levels/activity and aldosterone levels." (PMID 31543812, 2019). "Compensation of contracted plasma volume in Gitelman’s syndrome appears to occur through elevated aldosterone and renin and possibly other vasoconstrictor pathways." (PMID 31543812, 2019). "However, significant plasma volume depletion likely occurs in Gitelman’s syndrome based on the elevated plasma renin levels/activity and aldosterone levels." (PMID 31543812, 2019).
glaucoma (9 papers, 2018 to 2025). Increased pressure in the eyeball due to obstruction of the outflow of aqueous humor. "The renin-angiotensin system has also been implicated in the pathogenesis of glaucoma and RGC death." (PMID 30373222, 2018). "Multivariate analysesshowed a significant relationship between lower aqueous humor renin activityand primary open-angle glaucoma [coefficient (±SE): -0.029 ±0.013, p=0.026]." (PMID 32756783, 2020). "The renin-angiotensin system is involved in the pathogenesis of retinalischemic conditions and glaucoma." (PMID 32756783, 2020). "Our results showed that patients with primary open-angle glaucoma had loweraqueous humor renin activity." (PMID 32756783, 2020). "For instance, we have demonstrated in a proof-of-concept study that renin might be a therapeutic target in glaucoma." (PMID 32231590, 2020). "Patients with glaucoma arefrequently treated with topical b-blockers (e.g., timolol maleate 0.5%)and might exhibit lower local renin relea se to the AH." (PMID 32756783, 2020). "Based on preexistingdescriptions of increased ocular renin in glaucoma, as well as reduction of IOPfollowing treatment with renin inhibitors, our observation of significantly lower AHrenin activity in patients with POAG may be deemed contradictory." (PMID 32756783, 2020). "Similarly, the renin–angiotensin system may influence glaucoma by modulating intraocular pressure control." (PMID 40423075, 2025). "Moreover, human TM cells exposed to oxidative stress, a known etiology for glaucoma, selectively upregulated the RAPS ligand genes REN and AGT, while all the major RAPS components including their receptors were expressed at steady-state levels." (PMID 32707887, 2020). "Neither alocal increase in the consumption of renin nor a preferential shift toward bindingto the (pro)renin receptor and consequent activation of this alternative RAS pathwayhave been studied in eyes of patients with glaucoma." (PMID 32756783, 2020).
inflammatory bowel disease (9 papers, 2014 to 2024). A spectrum of small and large bowel inflammatory diseases of unknown etiology. "Interestingly, a recent pilot study revealed an up-regulation of the renin-angiotensin system in inflammatory bowel disease patients." (PMID 25207649, 2014).
insomnia (9 papers, 2017 to 2024). A sleep disorder characterized by difficulty in falling asleep and/or remaining asleep. "Supplementation of 500 mg of Mg has been associated with significant improvement in the insomnia severity index, sleep time, sleep efficiency, sleep onset latency, serum cortisol concentration, serum renin, and melatonin." (PMID 29093983, 2017). "Inflammatory state:Insomnia-(pw8b)-central nervous system-(pw25)-(pw66)-↑ghrelin:leptin-(pw67)-↑insulin resistance-(pw70)-↑angiotensin II-(pw88)-renin-(pw50)-↑TNF-α, IL-6-(pw41)-↑Inflammatory state." (PMID 35252372, 2022). "Second, activated sympathetic nerve activity due to insomnia, leading to increased renin release and tubular fluid reabsorption, may be associated with low serum sodium." (PMID 32891121, 2020). "Furthermore, sympathetic nerve activity due to insomnia may lead to increased renin release and tubular fluid reabsorption and may also be associated with low plasma sodium." (PMID 36359324, 2022). "Besides identifying the specific pathways involved, cluster analysis of these pathways is also unique to our study, such as the cAMP signaling pathway, renin secretion, and dopaminergic synapse; these three pathways function similarly or are more closely linked during ZSS treatment of insomnia." (PMID 34745308, 2021). "One potential explanation for this finding could be attributed to increased levels of renin, and aldosterone in this cohort due to an activated renin-angiotensinogen-aldosterone system (RAAS) thereby supporting the link between insomnia and serious cardiac events." (PMID 37733726, 2023).
myocarditis (9 papers, 2019 to 2023). Myocarditis is a condition that is characterized by inflammation of the heart muscle (myocardium). "Vitamin D supplementation prevents angiotensin II accumulation and decreases proinflammatory activity of angiotensin II by suppressing the release of renin in patients infected with COVID, thus reducing the risk of ARDS, myocarditis, or cardiac injury." (PMID 33142828, 2020). "Here, ACE, ARB, beta blocker and direct renin inhibitor treatment was effective in reducing inflammation in in vivo models of myocarditis." (PMID 31673885, 2019). "We aimed to ascertain the utility of beta blockers, calcium channel blockers and antagonists of the renin–angiotensin system in ameliorating myocardial injury, scar formation and calcification in animal in vivo models of myocarditis." (PMID 31673885, 2019).